MITF (melanocyte inducing transcription factor)
Diseases named in the same sentence as MITF in open-access papers (continued):
Sharing a sentence is not in itself a finding about the gene and the disease.
tumor (continued). "We demonstrated that the upregulation of INHBA initiated by FOXA2 promoted MITF-mediated EMT and tumor progression in response to sustained MMA stimulation." (PMID 38252148, 2024). "This previously unappreciated O-GlcNAcylation-MITF-mediate mechanism is corroborated in resistant patient-derived xenograft (PDX) lines, as well as tumor samples from patients who receive CDK4/6i treatment." (PMID 38961064, 2024). "MITF targets FZD7 promoter, and silencing MITF can promote tumor cell migration, invasion and colony formation in LUAD cells." (PMID 38872189, 2024). "On the other hand, miR-211 modulates the expression of genes involved in cell cycle regulation and tumour suppression, such as p16INK4A, BRN2, and MITF." (PMID 39594467, 2024). "Tumor cells showed discrete and overlapping expression of MET, Ecad and MITF and were co-expressed with NGFR in a small subset of tumor cells." (PMID 38386085, 2024). "Taken together, our results demonstrated that clones in the same tumor can naturally express less PRDX1, MITF, SOX10, PGC-1α, and pigmentation markers." (PMID 38790661, 2024). "Immunohistochemistry analysis showed that the tumor cells were positive to various extents for S100, SOX10, MelanA, HMB45, MiTF, and tyrosinase." (PMID 37373134, 2023). "This localization is exceptionally rare, but it can pose significant diagnostic challenges as rare cases of intraepidermal involvement have been reported, and the tumor cells are positive for melanocytic markers such as S100, SOX10, HMB45, MelanA, or MiTF." (PMID 37373134, 2023). "This not only correlates with the characteristic cytoplasmic findings, but it also explains the tumor’s positive immunohistochemical staining for TFE3 and wild-type MITF, as lysosomal inhibition induces activation of transcription factors MITF, TFE3, and TFEB." (PMID 37958362, 2023). "MITF promotes the transformation of saturated fatty acids into monounsaturated fatty acids by regulating SCD1 expression, thereby promoting tumor cell proliferation." (PMID 38065972, 2023). "MYC+MEL cells were increased in LN+AM and expressed high levels of MYC, MITF, SNAI2, and KIT, all of which play crucial roles in tumor progression." (PMID 38065972, 2023). "Our recent data show that MITF is required for GIST cell survival, proliferation, and tumor growth in xenograft experiments." (PMID 36834926, 2023). "Regarding α-Mangostin anti-tumor mechanism, we found that this xanthone down-regulated RAS, p-PI3K and MITF expression." (PMID 37575275, 2023). "Remarkably, this previously unappreciated O-GlcNAcylation-MITF-mediated mechanism was corroborated in resistant patient-derived xenograft (PDX) lines, as well as tumor samples from patients who received CDK4/6i treatment." (PMID 37886470, 2023). "Furthermore, copy number changes are also emerging, affecting MITF or MET (MET proto-oncogene and receptor tyrosine kinase) (amplifications), or the loss of the suppressor PTEN, increasing the genetic diversity of the metastases as compared to the primary tumor." (PMID 35628196, 2022). "We found that only five genes (MITF, CCR7, JAK1, ELN, and SLC6A4) functioned as tumor suppressors, whereas the remaining 17 genes functioned as oncogenes." (PMID 36425071, 2022). "On closer examination, MiTF, Melan-A, S100 and HMB45 staining revealed a cell line-specific distribution of tumor cells within the tissue models." (PMID 36175453, 2022). "We previously reported that silencing of SH3BP2 leads to a reduction of KIT expression at both mRNA and protein levels, as well as MITF at the protein level, resulting in a decrease in GIST tumor growth in vitro and in vivo." (PMID 36551682, 2022). "In immunohistochemical analysis, tumor cells were positive for human melanoma black 45 (HMB45) and microphthalmia transcription factor (MITF), and some cells even for α‐smooth muscle actin (αSMA), caldesmon and desmin." (PMID 33119872, 2021).
tumor (continued). "Our results showed that low-dose celecoxib can also normalize the tumor microenvironment, block the heterogeneous drug distribution and reduce both TGF-β and MITF expression in T + C group." (PMID 33922284, 2021). "MelanA, HMB-45, MITF, S100-protein, and SOX10 immunoreaction confirmed the melanocytic differentiation of this tumor." (PMID 34943200, 2021). "By immunohistochemistry, the tumor shows variable immunoreactivity for S100-protein, SOX10, and MITF, as well as specific melanocytic markers such as MelanA and HMB-45." (PMID 34943200, 2021). "Those mice, in which tumors were formed, had a significantly delayed tumor onset with a mean of 34 days as well as strongly decreased COX2 levels and increased MITF expression." (PMID 32978520, 2020). "Consistently, compared with the mimics control group, the tumor volume and tumor weight in the miR-876-5p mimics group were significantly reduced, which can be rescued by ectopic expression of WNT5A or MITF." (PMID 31171711, 2019). "In the tumor microenvironment, IL32 expression is highly correlated with genes related to T cell infiltration, and also positively correlates with high AXL/low MITF dedifferentiated gene signature." (PMID 30953519, 2019). "MITF is a driver of melanin synthesis and can activate the transcription of MET, an important receptor tyrosine kinase involved in tumor cell growth and release of extracellular vesicles." (PMID 30823658, 2019). "Tumor cells showed positive staining with anti-S-100, -HMB-45, and -MITF antibodies, consistent with typical CCS observations." (PMID 29879220, 2018). "The expression profile of MITF in PCa, together with its direct correlation with PGC1A, was suggestive of a tumor-suppressive activity of the transcription factor." (PMID 30310055, 2018). "Xenoplanted tumor cells exhibited the typical histopathological features of CCS and immunohistochemical profiles (i.e., positive for HMB45, S-100, and MITF)." (PMID 29879220, 2018). "In our study, the MITF-CRYAB transcriptional axis is reduced and exerts tumor-suppressive activity in PCa." (PMID 30310055, 2018). "The correlation analysis in PCa primary tumor specimens showed that a single gene, Crystallin Alpha B (CRYAB), had a consistent correlation (in more than 50% of datasets) with MITF, both the mean of isoforms and the individual isoform A." (PMID 30310055, 2018). "Allograft tumours from SC2 and SC4 express melanocyte genes and the proteins PMEL, MiTF and CATHEPSIN K." (PMID 29133867, 2017). "This was intriguing as it suggested that BQ788, despite enabling MITF up‐expression in the presence of BRAF inhibitor, had suppressed EDN1 expression within the tumours." (PMID 28606996, 2017). "This analysis also revealed a significant inverse correlation between MITF and NFIB expression in metastatic tumour lines, with MITF levels decreasing as NFIB levels increase (P < 0.0068)." (PMID 28119061, 2017). "Through its ability to modulate MAPK pathway activation and MITF expression, POU3F2 can suppress melanocytes differentiation and increase tumor metastasis." (PMID 27271588, 2016). "This was correlated with MITF target gene expression and tumor growth, where the BRAF inhibitor/nelfinavir combination led to an over 80% reduction in tumor volume." (PMID 26977879, 2016). "The overlap between the primary tumour classifying and cell line classifying systems allows us to infer that CITED1 expression is most likely restricted to a subset of MITF high ‘pigmentation’ subtype tumours." (PMID 25755924, 2015). "Some of these switches occur in known tumor drivers, including PPARG, CCND3, RALGDS, MITF, PRDM1, ABI1 and MYH11, for which the switch implies a change in the protein product." (PMID 25578962, 2015). "Interestingly, we found decreased expression of melanocyte differentiation markers in proliferative classified tumours, which indicate that a dedifferentiation process might be involved in the switch from MITF-high phenotype to a MITF-low (proliferative) phenotype." (PMID 24399611, 2014).
tumor (continued). "Immunohistochemical analysis was performed, which identified that the cells were positive for S-100, MITF and HMB-45 tumor markers." (PMID 25202380, 2014). "In our study, MITF and BCL2A1 were expressed in the melanospheres at levels similar to those in the tumor samples, which were higher than in the monolayers." (PMID 24733089, 2014). "MYC was upregulated in all tumor regions, but MITF activity varied—absent in P1 (dedifferentiated) and elevated in P3 and P4 (melanocytic)." (PMID 40669378, 2025). "We hypothesize that high MITF expression correlates with specific patterns of TIL infiltration within the BRISK category, reflecting a more immunogenic tumor microenvironment." (PMID 39976551, 2025). "Importantly, this study also shows that inhibiting MITF using ML329 affects imatinib-sensitive and -resistant cancer growth when the tumor is already established, increasing survival." (PMID 40343114, 2025). "No increase in natural killer (NK) cell tumor infiltration was observed in any of the single KOs or the MITF/TFEB DKO." (PMID 41275493, 2025). "Overall, this study suggests that more differentiated MITF+ tumors are efficiently targeted by immunotherapy, while AXL+ tumor cells may be more resistant, analogous to their response to targeted therapy." (PMID 39697983, 2024). "Our patient cohort also shows that immunotherapy-induced changes in the abundance of AXL+ or MITF+ tumor cells did not correlate with improved survival." (PMID 39697983, 2024). "Analyzing the parental MM tumors, we could detect a variable fraction of MITF−/low/CDH1−/ZEB1+/CD271+ cells, proposing the existence of a MIC subpopulation in the primary tumor mass." (PMID 38191367, 2024). "Of note, the administration of palbociclib treatment to PDX tumor-bearing mice also led to a substantial increase in the expression level of MITF compared to the group without receiving the drug." (PMID 37886470, 2023). "Immunohistochemistry (IHC) showed tumor cells diffusely expressed TFE3, and fluorescence in situ hybridization (FISH) demonstrated disruption of the TFE3 locus, confirming the diagnosis of Xp11.2 tRCC, the most common subtype of MiTF tRCC." (PMID 37528880, 2023). "Together, we propose the crucial role of the enhanced MITF-FAO axis in promoting LN metastasis, and blocking this axis may be a potential target for inhibiting tumor progression in AM." (PMID 38065972, 2023). "Using xenografted tumor models, we also found that reintroduction of WT MITF but not S49A mutant in MITF depleted-MCF-7 PR cells restored resistance to palbociclib." (PMID 37886470, 2023). "Furthermore, intrinsically resistant tumours seem to be in an alternative transcriptional state/phenotype, characterized by the activation of NF-kB and AXL signalling and low MITF activity." (PMID 35159327, 2022). "Similarly, in another study, a knock-down of MITF by shRNA in MM649 cells resulted in reduced cell proliferation in vitro and tumor growth and dissemination in vivo in mouse xenografts." (PMID 35159049, 2022). "By contrast, MITF, CCR7, JAK1, ELN, and SLC6A4 were lowly expressed in tumor tissues." (PMID 36425071, 2022). "APC/C (Cdh1) has a tumor suppressor function in melanocytes mediated by the subunit Cdh1, which inactivates PAX3 through ubiquitination and degradation, implying consequent inhibition of MITF production." (PMID 36274944, 2022). "As a result, several hub DEFs with maximum intramodular connectivity were identified (e.g., SOX4, EGR1, LEF1, FOS, MITF, KLF4, TCF7, and KDM6B), which might involve CD248-mediated tumor-promoting regulation in CAFs." (PMID 34970489, 2021).
tumor (continued). "In support of these speculations, the majority of relapsed tumours were found to have increased AXL and reduced MITF expression, similar to the escapee population observed here." (PMID 33741929, 2021). "Furthermore, melanocyte differentiation genes, including MITF, TYR, and TYRP1, were upregulated significantly by FR in class 1 relative to class 2 tumor biopsy samples." (PMID 33577798, 2021). "More importantly, we demonstrated that MITF regulates tumor progression in ccRCC cell via the RhoA/YAP signaling pathway; taken together, the results suggest that MITF could be a potential therapeutic target in ccRCC." (PMID 34208068, 2021). "As expected, and in contrast to the MITF-positive parental cells, inactivation of CD8+ T cells did not increase tumor load in mice injected with irradiated B16/F10-MITF-KO cells." (PMID 33789714, 2021). "Collectively these observations indicate that MITF can be induced in response to irradiation, with increased MLANA antigen expression correlating with the irradiation-induced immune response that prevented tumor formation in mice." (PMID 33789714, 2021). "This is because in vitro, in the absence of signalling from the tumour microenvironment, each phenotype‐specific epigenetic background is incompatible with sustained genetic manipulation of MITF expression." (PMID 32145051, 2020). "The tumor cells were negative for any other melanocytic markers such as S100, Melan A, MITF, SOX10, all myogenic markers (SMA, MSA, desmin, caldesmon) and cytokeratins." (PMID 31309284, 2020). "Therefore, accumulating evidence indicates that MITF has an important impact on immune function and the response to ICT, acting both on tumor immunogenicity and in shaping the immunological TME." (PMID 33276788, 2020). "Since the bound fraction determines transcription burst frequency, our results are consistent with the K243Q or acetylated WT MITF, but not the K243R mutant, supporting melanocyte development and promoting tumor growth." (PMID 32531202, 2020). "However, if these tumours progress with ERK reactivation, the expression of PAX3, BRN2, and MITF should be restored." (PMID 30277012, 2019). "This network demonstrates that 61 exosomal molecules may affect tumor progression through pathways controlled by key components including MET, Ras, RAF1, Mek, ERK1/2, MITF, BCL2, PI3K, Akt, mTOR, PD-1, KIT, JAK STAT3, or ETS1." (PMID 31681332, 2019). "In the context of nutrient starvation in the tumor microenvironment, activation of the translation initiation factor eIF2B leads to both translational inhibition and ATF4-mediated transcriptional downregulation of MITF." (PMID 31118886, 2019). "The tumor cells were diffusely positive for factor XIIIa and ALK, but were negative for AE1/AE3 keratin, alpha-smooth muscle actin, CD30, CD34, CD68, PU.1, melan A, MITF, and S-100 protein." (PMID 29747676, 2018). "Furthermore, knockdown of TFE3 and MITF can abolish xenograft tumor growth of PDA cells, while MITF overexpression in KrasG12D mouse PanIN cells promoted tumorigenesis upon orthotopic injection." (PMID 29903018, 2018). "Interestingly, MITF knockdown also led to increased CCL-2 levels, which were involved in the tumor-promoting effect." (PMID 30237393, 2018). "We argue that such cells either die due to the lack of MITF antiapoptotic function, as already documented in 501mel cells 27, or continue growing as an undifferentiated tumour if antiapoptosis is provided by other genes." (PMID 29369499, 2018). "Depletion of MITF from the population caused a decrease in both number and size of lung metastases while BRN2 depletion similarly resulted in a reduction in tumor burden overall but did not significantly reduce the total number of metastases." (PMID 28883623, 2017). "A similar heterogeneity was seen in other tumour samples from patients on treatment, even when the overall expression level of MITF did not increase." (PMID 28606996, 2017).
tumor (continued). "Quantitative RT-PCR on tumor cells revealed massively elevated levels of MITF mRNA as compared to (i) primary FH-hTERT cells, (ii) non-malignant FH-hTERT regeneration clusters, but also (iii) the observed polyclonal tumor." (PMID 29383183, 2017). "Overall our data lead to a model, whereby in tumours on treatment with BRAF inhibitor‐induced MITF up‐expression in MITF‐high cells increases intra‐tumour EDN1 levels, which can act on MITF‐high (paracrine or autocrine) as well as AXL‐high cells to re‐activate ERK." (PMID 28606996, 2017). "Although this has been interpreted as a reflection of a BRN2 suppressor role, the fact that, in other areas of the same tumour, BRN2 and MITF are intensely co‐expressed suggests that the situation is more complex and that local microenvironment‐derived signals are also relevant." (PMID 25818589, 2015). "On the other hand, subpopulations of AXL+/WNT5A+ MITF‐negative cells can escape therapy and thus will be able to re‐establish tumour growth." (PMID 25818589, 2015). "Finally, G‐protein‐coupled receptor/cAMP‐induced MITF upregulation confers MAPK pathway inhibitor resistance, and enhanced CREB phosphorylation is detected in tumours of relapsed patients." (PMID 25818589, 2015). "Immunohistochemical analysis indicated positive staining for tumor markers S-100, MITF and HMB-45, and negative staining for CD10, CD68, actin, desmin and AE1/AE3 antigens (data not shown)." (PMID 25202380, 2014). "Tumour oncogenes include SPP-1, MITF, CITED-1, GDF-15, c-Met, and HOX loci." (PMID 23091727, 2012). "Although the directs targets of BAP1 have not been fully elucidated, other melanocyte-specific tumor proteins, such as MITF, have been shown to be regulated by another deubiquitinating enzyme, named ubiquitin-specific protease 13 (USP13)." (PMID 22545102, 2012). "This suggests that quiescent cells, regardless of their differentiation status as defined by MITF levels, may exhibit a more aggressive phenotype, including increased invasiveness, drug resistance, and tumor initiation potential." (PMID 40528051, 2025). "We observed that MITF overexpression in zebrafish resulted in a significant increase in the induction of crestin:EGFP at six weeks post-fertilization and had significantly accelerated tumor onset compared to mcr:Empty controls as expected due to the oncogenic properties of MITF." (PMID 39277608, 2024). "Moreover, analyses of SOX10– and SOX10+MITF– tumors developed in NSG mice at molecular level suggested a profound difference between the tumor types and reflected the tumor growth difference and sustained increased expression of NGFR, JUN, and WNT5A in the SOX10+MITF– melanoma tumors." (PMID 36040798, 2022). "It is also unclear from analysis of MITF target genes why low MITF expression is related to an increase in tumor‐infiltrating immune cells nor how in the same cells it may repress or activate different sets of genes." (PMID 35771179, 2022). "Moreover, distinct transcriptional states characterized by variable MITF expression and activity show different responses to MAPK pathway inhibitors, highlighting how tumor heterogeneity and plasticity could be drivers of MAPK inhibitor resistance." (PMID 35912100, 2022). "By contrast, a remarkably different response was observed after injection of irradiated B16/F10-MITF-KO cells into athymic nude mice where non-irradiated cells readily formed lung tumors, but no tumor formation was observed after injection of irradiated MITF-KO cells." (PMID 33789714, 2021). "As the MITF/PTEN groups were independent of tumor genetic mechanisms, we wanted to elucidate whether any underlying transcriptional differences could be discerned." (PMID 32245160, 2020).